KIT (KIT proto-oncogene, receptor tyrosine kinase)
Diseases named in the same sentence as KIT in open-access papers (continued):
Sharing a sentence is not in itself a finding about the gene and the disease.
leukemia (continued). "Furthermore, with the development of NGS in recent years, the pathological and clinical roles of KIT mutations in AML other than CBF leukemia have also attracted attention." (PMID 35563085, 2022). "The KIT exon 17 mutation is particularly enriched in AML1/ETO-positive leukemias." (PMID 34331016, 2021). "KIT mutations are present in about 25% of CBF leukemias and are associated with inferior outcomes." (PMID 34331016, 2021). "Furthermore, we have shown that DBF induces significant alterations in expression of genes encoding tyrosin kinase receptors which are involved in leukemia progression (KIT, VEGFR, PDGFR)." (PMID 34564151, 2021). "Although spatio-temporal analyses of KITD816V signals have been performed, it is unclear whether the N822K mutation in leukemia affects KIT localization and the signal platform." (PMID 31484543, 2019). "In patients with leukemia, KIT mutations can suggest a greater risk of relapse." (PMID 29796159, 2018). "KIT mutations in CBF leukemias are associated with shorter survivals." (PMID 27023522, 2016). "Mutations in KIT help to refine prognosis in core binding factor leukemia." (PMID 26239249, 2015). "To exclude cell line-specific off-target biology interfering with the effects of kinase-inhibition, we tested leukemia-driving RTK mutations in an isogenic cellular background: Various human (mutant) FLT3 or KIT isoforms were stably transfected in the IL3-dependent murine pro B-cell line Ba/F3." (PMID 23497317, 2013). "Structural considerations suggest quizartinib could inhibit other members of the class III RTK family that are frequently mutated in leukemia or myeloproliferative disorders (i.e. KIT and PDGFR)." (PMID 23497317, 2013). "In addition, we analyzed several native CBF leukemia samples, known to highly express CD117 (KIT) and harboring gain-of-function mutations in 40% of cases: Samples were treated with crenolanib in a dose-dependent manner for 48 hours and reduction of the CD45-low viable cohort was followed." (PMID 29137311, 2017). "Leukemia characterized by mutation of CCDC26 might be effectively treated by KIT-targeted therapy." (PMID 25928165, 2015). "We sorted CM+, GFP+ leukemia cells for KIT and CSF2RB, markers we previously showed distinguish between these two populations in this mouse model, and performed PLA for RUNX1 and PTPB1." (PMID 41214140, 2026). "Downregulation of Pax5 and upregulation of Myc was validated via qRT-PCR analysis in 2 additional independent Pax5± pre-leukemic mice (pre-leukemia 5 and 7) displaying the c-KIT+ CD25+ cell population." (PMID 40394211, 2025). "Our analysis of a c-KIT+ CD25+ cell population identified in the BM of an ageing Pax5± cohort (termed pre-leukemia) supports this assumption, since these cells had already started to lose their B-cell identity." (PMID 40394211, 2025). "The leukemias displayed a precursor B-cell surface phenotype of B220+ CD19− IgM− together with variable c-KIT and CD25 expression." (PMID 40394211, 2025). "Leukemia-initiating cells in a CML blast crisis mouse model had variable c-KIT expression, whereas leukemia-initiating cells in chronic-phase CML were present in the c-KIT–positive fraction." (PMID 36413413, 2023). "We conclude that CML LT-HSCs expressing low c-KIT levels are enriched for primitive, quiescent, drug-resistant leukemia-initiating cells and represent a critical target for eliminating disease persistence." (PMID 36413413, 2023). "Normal hematopoietic cells express only a few c-KIT; while c-KIT is a leukemia stem cell marker, it is overexpressed to influence the malignant phenotype in AML cells." (PMID 36232694, 2022). "We further show that de novo human AML also express tnFGFR1 which correlates with upregulation of FLT3 and KIT as in mouse leukemia cells." (PMID 35906694, 2022). "AML1-ETO alone fails to induce leukaemogenesis; an additional coinciding mutation such as KIT, FLT3, JAK2, RAS, and PDGFR, is needed for full-blown leukaemia." (PMID 33833412, 2022).
leukemia (continued). "Approximately two-thirds of CBF leukemia cases harbor activating mutations in NRAS, KIT, FLT3, KRAS, PTPN11, and/or loss-of-function mutations in NF1." (PMID 34331016, 2021). "We exposed four leukemia and four NB cells to multi-kinase (KIT, PDGFRa, and PDGFRb) inhibitor-imatinib in the presence of belinostat or hydrazostat." (PMID 34944663, 2021). "Gain of function mutations in KIT have been found in 2% of AML overall and in a 33% of the CBF leukemias." (PMID 34660311, 2021). "The addition of the multikinase inhibitor dasatinib to a conventional chemotherapy backbone represents a prominent example of such an approach—exploiting the frequent occurrence of KIT mutations and higher KIT expression levels in CBF leukemia." (PMID 34331016, 2021). "Mutations in the receptor tyrosine kinase genes KIT and FLT3 and the proto-oncogenes NRAS and KRAS have been observed in up to 80% of CBF leukemia patients and probably serve as cooperating factors during leukemogenesis promoting proliferation." (PMID 31896782, 2020). "When these cell lines were treated with 7.0 μM CPZ for 72 h, CPZ drastically (more than 90%) inhibited the growth and survival of MV4-11 and HMC-1 but showed only marginal (0–40%) inhibitory effects on leukemia cell lines with FLT3 WT/KIT WT." (PMID 32811837, 2020). "Direct flow cytometry analysis of alive leukemia cells confirmed that 100% of Kasumi-1 cells had surface KIT expression, and K562 cells had a sizeable KIT-positive population." (PMID 31681584, 2019). "Further analyses of the localization and functions of these negative regulators should explain how KIT signaling is inactivated in the ER, PM, and EL both in leukemia and GISTs." (PMID 31484543, 2019). "We observed that the expression of CSF2RB, IL1RL1, and KIT in recipient leukemia samples was similar to that of the original, donor leukemia samples, regardless of the sub-population transplanted." (PMID 30742053, 2019). "We found that the CSF2RB− IL1RL1+ KIT+ population had the highest BrdU incorporation rate, which correlated with the fastest leukemia development after transplantation." (PMID 30742053, 2019). "In this study, blockade of the ER export of KIT with BFA/M-COPA decreased KIT’s autophosphorylation in leukemia cells." (PMID 31484543, 2019). "Taken together, these results suggest that the Golgi apparatus serves as the platform for KIT activation in leukemia cells." (PMID 31484543, 2019). "Collectively, in these leukemia cells, newly synthesized KIT in the ER moves to the PM along the secretory pathway and subsequently traffics to EL through kinase activity-dependent endocytosis." (PMID 31484543, 2019). "Our current findings disclose that these genetically homogeneous leukemia cells, in terms of BCR/ABL, KIT or FLT3 mutations, are epigenetically heterogeneous and can be distinguished by overexpression of FTO and reduction of m6A methylation." (PMID 30297871, 2018). "Gene set enrichment analysis (GSEA) confirmed that co-expression of IRX3 with Hoxa9 led to repression of a mature myeloid lineage program in KIT+Gr1+ leukemia cells, in keeping with morphologic analysis." (PMID 29346763, 2018). "To evaluate the consequences for the transcriptome of co-expression of IRX3 with Hoxa9, we performed RNA sequencing of flow-sorted KIT+Gr1+ leukemia cells recovered from the BM of sick mice, three from each cohort." (PMID 29346763, 2018). "Oncogenic mutations, that are found in KIT in many types of cancer and leukemia, result in dysregulated KIT activation and thus aberrant activation of downstream signaling." (PMID 29686302, 2018).
leukemia (continued). "The KIT inhibitor dasatinib is currently being tested in clinical trials for the treatment of core binding factor leukemias (clinicaltrials.gov; NCT02013648, NCT00850382, NCT02113319)." (PMID 29137311, 2017). "Imatinib, a FDA-approved tyrosine kinase inhibitor specific for oncogenic fusions or mutations of PDGFRs, c-KIT, and ABL tyrosine kinase oncogenes, has been an effective or even curative treatment for certain leukemias." (PMID 27259262, 2016). "Expression of KIT in leukemia stem cells (LSCs) from pediatric AML patients who relapsed after chemotherapy was increased compared with that in patients who did not relapse." (PMID 25928165, 2015). "The target of ‘Dasatinib’ is ‘Tyrosine-protein kinase ABL1’ (ABL1: BCRABL), the disease gene of ‘Leukemia, Acute Myeloid; Aml’ is ‘Mast/stem cell growth factor receptor Kit’ (KIT)." (PMID 24244318, 2013). "Various FLT3 or KIT leukemia cell lines and native blasts were used to determine the antiproliferative and proapoptotic efficacy of quizartinib." (PMID 23497317, 2013). "Consistently, this miRNA cluster is frequently downregulated in CBF leukemia patients, concomitantly with the upregulation of its target KIT." (PMID 23344057, 2013). "Point mutations in kinase domains of RTKs such as EGFR, HER2, MET, KIT, and FLT3 (among others) have been implicated as driver mutations in various cancers such as lung, breast, renal, liver, intestinal, and leukemia." (PMID 22347506, 2012). "CCDC26, a long noncoding RNA located within the ~2 Mb MYC locus and frequently amplified in leukemia, has been shown to regulate acute myeloid leukemia cell proliferation through KIT signaling and to influence erythroid differentiation via FOG-2–mediated transcriptional control of globin genes." (PMID 41509392, 2025). "In the meantime, we have applied this experimental procedure to breast cancer (MCF-7 and T47D) and leukemia (HEL) cell lines tagging either E-cadherin or CD117 encoded by KIT, respectively (data not shown)." (PMID 37178110, 2023). "As with other tyrosine kinase activating mutations, studies have shown that activating mutations in KIT are not sufficient to cause leukemia but cooperate with other driver mutations to transform leukemic cells." (PMID 35756660, 2022). "Through the analysis of transcriptomic data of 701 leukemia and NB patient samples and cell lines, we revealed that the expression of RTK, such as KIT, FLT3, AXL, FGFR3, and NTRK1, is linked with HDAC class I. Although HDAC inhibitors have antitumor activity, they also have high whole-body toxicity." (PMID 34944663, 2021). "Additionally, KIT was one of the top-scoring genes with the highest HDAC SCORE for leukemia patients and was among top genes in NB patient analysis." (PMID 34944663, 2021). "Mutations in DHX15 and SMC1A correlated with shorter OS in RUNX1/RUNX1T1 leukemia (DHX15: HR = 3.57, p = 0.02; SMC1A: HR = 6.47, p < 0.001), while point mutations in KIT at position D816 correlated with reduced RFS in RUNX1/RUNX1T1 leukemia (HR = 2.27, p = 0.046)." (PMID 31896782, 2020). "We hypothesized that in some cases the examination of the expression level of KIT and TrkA receptors is insufficient for understanding leukemia and NB cell behavior in the presence of exogenous proteins, NGF, and SCF." (PMID 31681584, 2019). "Mice transplanted with CSF2RB− IL1RL1− KIT− cells had the longest time to leukemia development and the lowest penetrance with statistically significant differences in survival as compared to mice transplanted with CSF2RB−, IL1RL1−, KIT+/− cells at the 10,000 cell dose." (PMID 30742053, 2019). "We next examined the site of KIT activation in leukemia cells." (PMID 31484543, 2019). "Moreover, from a clinical point of view, our findings offer a new strategy for leukemia treatment through that blocks the incorporation of KIT mutants into the lipid rafts of the Golgi." (PMID 31484543, 2019). "We then considered the role of PTPs in KIT inactivation in the ER in leukemia cells." (PMID 31484543, 2019).
leukemia (continued). "Interestingly, miR-29b plays a critical role in c-KIT oncogene expression regulation in CBF leukemia by dampening c-KIT oncogene transcription through the direct targeting of its activator Sp1." (PMID 29435107, 2018). "Repression of miR-221 by RM8 in leukemia cells with a KIT activating mutation is expected to exacerbate proliferation relative to RM8-positive leukemia cells with a non-mutated KIT." (PMID 29156756, 2017). "Remarkably, KIT is often overexpressed in CBF leukemia concomitantly with miR-222-221 downregulation, suggesting that miR-222-221 may be under the transcriptional control of CBF (i.e., RUNX1 and CBFB)." (PMID 23344057, 2013). "In CBF AML, which is frequently dependent upon KIT-mediated (gain-of-function) signal transduction, quizartinib demonstrated varying antiproliferative and cytotoxic efficacy in in vitro and ex vivo leukemia cells – in some cases within the low nanomolar range of FLT3 ITD (JM) positive samples." (PMID 23497317, 2013). "Indeed, type I mutations are common in NUP98 rearranged leukemia, including mutations in the NRAS, KRAS, KIT, WT1 and FLT3 genes." (PMID 23332017, 2013). "That some MYB target genes (such as KIT, CDK6 and FLT3) exhibit a degree of correlation with MYB levels amongst the patient datasets probably reflects a wide range of driver mutations and a very heterogeneous genetic landscape amongst the complex karyotype leukaemias." (PMID 37996430, 2023). "In addition, HR and/or c-NHEJ deficiency could be induced by the treatment of leukemia/solid tumors with the tyrosine kinase inhibitors (TKi) against the cancer-driven oncogenic tyrosine kinases (e.g., FLT3(ITD), JAK2(V617F), c-KIT(N822K), IGF-1R, EGFR)." (PMID 36497275, 2022). "Although this subset of patients is small in number, these observations raise the interesting question of whether KIT mutations are associated with an elevated risk of chromosomal abnormality in non-CBF leukemia." (PMID 35563085, 2022). "In non-CBF leukemia with KIT mutation, three of five patients (Nos." (PMID 35563085, 2022). "We then examined whether KIT activated downstream molecules on the Golgi in leukemia cells." (PMID 31484543, 2019). "Furthermore, blockade of mutant KIT incorporation into the lipid rafts may provide a new strategy for suppression of growth signals in leukemia cells." (PMID 31484543, 2019). "As expected, several previously reported genes with abnormal methylation in leukemias such as CPEB1, BLK, FLT3, ZCCHC7, EBF1, HDACs, IKZF1, RB1, CDK6, DOCK5, DPP10, MUC4, JAKs, KIT, KRAS, LINC01013, MAD1L1, NOTCH1, and STATs, among others, were also detected." (PMID 41226303, 2025). "Subsequent, propagation and transplantation of the MLL-AF9 transduced c-KIT+ cells in recipient mice led to AML, and leukaemia cells from these mice were used for further analysis." (PMID 40425534, 2025). "Using a combination of a mouse model of ETP-ALL and patient-derived xenografts, we identified leukemic cells co-expressing KIT and high levels of FLT3 (KF) that were most enriched for leukemia initiating activity, self-renewal, and chemoresistance." (PMID 39849166, 2025). "CD117/KIT expression is a marker of GATA1s-induced pre-leukemia- and GATA1s/STAG2-knock-out-induced leukemia-initiating cells." (PMID 36035173, 2022). "In summary, the combinatorial blockade of the EZH2 and BCL-2 shows a great synergistic anti-leukemia effect through upregulated PIK3IP1 and downregulated c-KIT." (PMID 36232694, 2022). "Both c-KIT and CD34 are hematopoietic stem/progenitor markers; particularly, c-KIT is also the leukemia stem cell marker." (PMID 36232694, 2022). "Cabozantinib (XL184) targets VEGFR2, c-MET, KIT (also known as CD117), AXL, and FLT3; and induces apoptosis in FLT3-ITD+ leukemia cells in a dose-dependent manner." (PMID 31694201, 2019).
leukemia (continued). "Thus, considering the high frequency class I mutations (especially in KIT, FLT3 and RAS genes) in CBF-AML, it is likely that CCDC26 disruption could highlight a new class I aberration leading to increased cell survival and proliferation in leukemia." (PMID 29464086, 2018). "We now provide proof of antileukemic efficacy in a patient with relapsed mutant-KIT D816V positive CBF AML – and point to an unexpected mode of action via release of the differentiation blockage and maturation of leukemia blasts." (PMID 29545943, 2018). "Considering that Sp1/NFkB is also involved in the regulation of receptor tyrosine signaling, we examined the changes of two receptor tyrosine kinases, KIT and FLT3, which play a pivotal role in leukemia pathogenesis." (PMID 28415607, 2017). "Because our studies and others demonstrated that Sp1/NFkB is also involved in the regulation of tyrosine kinase signaling, as a proof of concept, we examined the changes of KIT and FLT3, the key regulators of leukemia pathogenesis." (PMID 28415607, 2017). "Kinase inhibition of (mutant) KIT, PDGFR and FLT3 isoforms by quizartinib leads to potent inhibition of cellular proliferation and induction of apoptosis in in vitro leukemia models as well as in native leukemia blasts treated ex vivo." (PMID 23497317, 2013). "Quizartinib potently inhibits cellular proliferation and induces apoptosis in leukemia cell lines that are dependent on FLT3, KIT or PDGFRA activity." (PMID 23497317, 2013). "IMATINIB, a tyrosine kinase inhibitor, targets c-KIT and disrupts downstream MAPK and AKT signaling pathways essential for leukemic cell survival and proliferation, making it a promising therapeutic candidate for leukemia." (PMID 41171828, 2025). "Previously, we reported that, unlike normal KIT, mutant KIT (KITmut) in leukaemia cells and GIST is localised to intracellular compartments where it can be autophosphorylated and activated." (PMID 40770227, 2025). "Concurrently, Dovitinib, targeting FLT1, EGFR, FLT3 and KIT, acts as a EGFR inhibitor and FLT3 inhibitor, with previous research showing Dovitinib showed treatment efficacy in naïve and imatinib-resistant BCR::ABL(+) leukemia cells." (PMID 39247833, 2024). "Moreover, TQ treatment reduces the upstream effectors of STAT5, such as KIT and FLT3, leading to dephosphorylate STAT5 in leukemia cells." (PMID 35337104, 2022). "We measured the expression of genes coding RTKs: FLT3, KIT exclusively in leukemia cell lines, PDGFRa, AXL in NB, NTRK1, FGFR3, INSR, ROR2, and RET in both NB and leukemia cells by qRT-PCR, which were top-scoring RTK-coding genes among leukemia and NB cell lines." (PMID 34944663, 2021). "We used leukemia cell lines, such as Kasumi-1 (KITN822K, AML), SKNO-1 (KITN822K, AML), and HMC-1.1 (KITV560G, MCL), to explore how KIT transduces signals in these cells and to examine the signal platform for the mutants using immunofluorescence microscopy and inhibition of intracellular trafficking." (PMID 31484543, 2019). "To test whether IL1RL1 and KIT can be used to isolate cells with LSC activity in vivo, we performed LDA using leukemia samples from three independent Cbfb-MYH11 expressing mice." (PMID 30742053, 2019). "In fact, the dynamic expression of KIT and IL1RL1 in leukemia cells suggests that these receptors may be regulating cell processes other than differentiation." (PMID 30742053, 2019). "Mice transplanted with the CSF2RB− IL1RL1+ KIT+ cells showed the shortest average life span and highest penetrance of leukemia development with statistically significant differences in survival as compared to mice transplanted with CSF2RB−, IL1RL1−, KIT+/−, or CSF2RB+ cells at the 10,000 cell dose." (PMID 30742053, 2019). "To determine whether IL1RL1 continues to be expressed in the LSC-enriched CSF2RB− population after leukemic transformation, we stained leukemia cells isolated from Cbfb+/56M, Mx1-Cre+ mice for IL1RL1 and KIT." (PMID 30742053, 2019).